IGF2 (insulin like growth factor 2)
Diseases named in the same sentence as IGF2 in open-access papers (continued):
Sharing a sentence is not in itself a finding about the gene and the disease.
tumor (continued). "Key components of the IGF axis, including IGF2, IGF1R, and IGFBP3, are frequently dysregulated in HB, promoting tumor development and metastasis." (PMID 40136353, 2025). "Tumor clusters c1–c4 exhibited relatively high expression of EPCAM and KRT18, with c4 showing elevated IGF2 expression." (PMID 40098972, 2025). "Our group recently discovered that oHSV infection stimulates insulin-like growth factor 2 (IGF2) secretion, which in turn activates the insulin-like growth factor 1 receptor (IGF1R)-AKT signaling throughout the tumor microenvironment (TME)." (PMID 41510300, 2025). "GHRH antagonists exert their antitumor activity by binding to GHRH-R and SV1, thereby disrupting the autocrine/paracrine mitogenic signaling mediated by tumor-derived GHRH, IGF1, and IGF2." (PMID 40244089, 2025). "IGF-2 and IGFBP2 secreted by tumor cells upregulate the glycolytic pathway of bone marrow stromal cells and promote tumor cell proliferation and metastasis." (PMID 40165895, 2025). "In summary, we identified a novel subset of CD34+CLDN5+ECs, with distinct senescent cellular features and high expression of IGF2, which was regulated by CEBPβ, primarily existed in the HCC tumor tissue." (PMID 39674501, 2025). "Other notable NET-related CSM and SP genes include previously discussed IGF-2 and IGFBP3 genes and genes related to the stromal component of the tumor (COL5A3, FN1, and NOTCH3)." (PMID 40522948, 2025). "In our functional enrichment analysis, we identified several common interacting protein-coding genes within the IGF2BPs gene family including IGF2, HMGA2, and LIN28A/B, all of which are known to facilitate tumor progression." (PMID 40088376, 2025). "The other IGF receptor, the IGF-2/mannose-6-phosphate receptor (IGF-2R), lacks a kinase domain and functions as a scavenger receptor that degrades IGF-2, thereby acting as a tumor suppressor." (PMID 41002547, 2025). "Flow cytometric analysis showed elevated IGF2 expression in the CAFs compared with expression levels in immune cells (CD45+ subsets) or malignant cells in both human and murine tumor tissues." (PMID 39545420, 2024). "Ct values of IGF2 and INS-IGF2 normalized to GAPDH, were used to calculate ΔCt values, and relative expression was derived by dividing 2−ΔCt for tumor vs adjacent normal tissue within each group." (PMID 39593106, 2024). "Based on the Tumor Immune Estimation Resource (TIMER) database, we identified a positive correlation between IGF2 expression and the infiltration level of CAFs in both BRCA and COAD." (PMID 39545420, 2024). "CAFs secrete high levels of the ligands IGF1 and IGF2, thereby promoting the tumor growth, migration, and invasion as well as drug resistance of IGF1R-expressing tumor cells." (PMID 38892104, 2024). "It is noteworthy that IGF2 sends signals through IGF1R, one of the key receptor tyrosine kinases involved in tumor development." (PMID 39711843, 2024). "Our findings highlight the role of TGF-β in upregulating IGF2 in CAFs, underscoring the cytokine’s vital involvement in CAF regulation and its diverse effect on shaping an immunosuppressive tumor microenvironment." (PMID 39545420, 2024). "The proposed mechanism of IGF-2-mediated hypoglycemia involves excess tumour production of mature IGF-2 and immature ‘big’ pro-IGF-2, which bind to IGF receptors and insulin receptors." (PMID 38432069, 2024). "The relevance of prognostic biochemical, histological, and imaging parameters, such as IGF-2 levels, vimentin, CD34, bcl-2, or CD99 positivity but cytokeratin negativity, and tumor size > 10 cm, is unclear." (PMID 39138498, 2024). "Remarkably, Igf2–/– mice exhibited heightened infiltration of CD8+ T cells and reduced tumor burden in comparison with WT mice." (PMID 39545420, 2024). "Top differentially suppressed genes as the tumor transformed included SMOC1, BCAN, NES, AIF1L, ENC1, and IGF2 (p < 0.01)." (PMID 39256867, 2024).
tumor (continued). "This is especially true because LOI has been found to occur early in carcinogenesis, which means that some of these tumor-adjacent tissues have started the oncogenic transformation, with LOI in IGF2 as one of the early hallmarks." (PMID 39199324, 2024). "For example, insulin-like growth factor 2 (IGF2) is a paternally expressed imprinted gene on chromosome 11, and LOI was demonstrated in ccRCC and several other tumor types." (PMID 39199324, 2024). "IGF-1 and IGF-2 are known to enhance BC cell proliferation in vitro, and mouse models show that IGF-1R signaling promotes tumor growth in distant tissues." (PMID 39273251, 2024). "At post-transcriptional levels, microRNAs (miRs), long non-coding RNAs (lncRNAs) and RNA-binding proteins, such as the family of N6-methyladenosine (m6A) readers RNA-binding proteins IGF2BPs, regulate the stability of IGF2 and IGF1R in tumor cells." (PMID 38892104, 2024). "In this study, we discovered a novel mechanism of resistance to oHSV therapy in which viral therapy-induced IGF2 expression and secretion activates IGF2/IGF1R signaling in tumor and TME cells." (PMID 38853689, 2024). "RNA sequencing demarcated tumor models from normal liver cells by displaying high levels of the HB markers GPC3, AFP and IGF2, the proliferation marker Ki67, and the Wnt signaling target AXIN2." (PMID 39529166, 2024). "The silencing of IGF1R or treatment with antibodies binding IGF1 and IGF2, BI836845 or xentuzumab inhibited the growth of in vivo cocultured CAFs-tumor cell xenografts." (PMID 38892104, 2024). "IGF2BP3 is an RBP and can affect tumor progression by targeting mRNA for MMP1, CD44, CDK164, ABCG2, IGF2 and other genes." (PMID 37340423, 2023). "Among HB without mosaicism, tumors with 11p15.5 alteration showed a higher IGF2 expression (P = 0.01) and a lower H19 and CDKN1C tumor suppressor expression (P = 5.3 x 10−8 and P = 4.0 x 10−3, respectively)." (PMID 37932266, 2023). "Cancerous thyroid cells can produce IGF-1 and IGF-2 locally: stromal cells secrete IGF-1, while IGF-2 is produced by tumor cells." (PMID 36811728, 2023). "The IGF2 protein has a tumour-promoting effect on existing colorectal neoplasia and that LOI of IGF2 in either tissue or peripheral blood leukocyte (PBL) samples is associated with an increased risk of CRC." (PMID 37213278, 2023). "BCa cancer cells’ survival and spheroid-forming capability enhancement were induced by AKT phosphorylation due to IGF2/IGF1R induction, which was thought to be involved in molecular mechanism of SOX2 expression leading to poor tumor prognosis." (PMID 37196048, 2023). "The expression profiles of genes in the first cluster across all tumours (TOP2A, CDK1, BIRC5, GPC3, IGF2 and AFP) were strongly correlated." (PMID 36345011, 2022). "Both pathways utilize dysregulation of 11p15 genes as a driver of oncogenesis, either resulting in a tumor arising directly in isolation through LOH of 11p15, or indirectly via clonal nephrogenesis with perturbation of 11p15 by GOM of H19/IGF2:IG DMR." (PMID 35804856, 2022). "The identification of human disorders due to impaired IGF2 gene expression has also helped to elucidate the major role of IGF-II in growth and in tumor proliferation." (PMID 35741015, 2022). "We thus concluded that tumor cells, especially in the G2 stage, are sensitized for IGF1, IGF2 and Insulin stimulation by increased glucose in the TME, as these growth hormones can activate IGF1R." (PMID 35574343, 2022). "The IGF2 neutralizing antibody and autophagy inhibitor 3-MA consistently reduced the CAF-promoted tumor relapse in tumor-bearing mice after radiotherapy." (PMID 36010899, 2022). "miR-185-5p targets ROCK2, ELK1, ELK3, IGF2, RAGE, BCL2, BCL2L1, and many other genes to suppress tumor cell migration and invasion." (PMID 35223832, 2022).
tumor (continued). "Interestingly, the effect of the tumor-activated versus control SCs on SCLC cell invasiveness was significantly higher, and this was associated with a higher level of expression of several genes, including the STAT3, SOCS3, BCL6, ELF3, IGF2, and IL32 genes, in SCLC cells." (PMID 36551618, 2022). "CAFs-3 from the primary tumor showed distinct expression of other chemokines and growth factors, such as C3, CCL5, IGF1, CXCL10, CXCL9, and CXCL14, in addition to CCL19 and IGF2." (PMID 34790166, 2021). "But recent advances, including the first ileal NET mouse model as well as methods for culturing patient tumor samples, have been described and have already helped to identify IGF2 and CDK4 as two of the genetic drivers for this tumor type." (PMID 34680217, 2021). "Levels of IGF2 messenger RNA and protein increase > 20-fold in 15% of human HCC tissues compared with non-tumor liver tissues." (PMID 34714420, 2021). "Enhanced translation of IGF2 and IGF1R occurs via the de novo expression of the oncofetal RNA-binding proteins IGF2BPs (IGF2BP1, IGF2BP2, IGF2BP3) in different tumor types." (PMID 34440844, 2021). "Both the FF-induced tumor and IGF2-induced tumor, when transplanted to a new recipient, rapidly grew the same CD3(+)/CD20(-) tumor after two weeks." (PMID 34539876, 2021). "It is also reported that HIF-1 regulates insulin-like growth factor 2 (IGF-2), a crucial survival factor, in hypoxic tumor cells." (PMID 34639215, 2021). "Compared with CAFs at the primary site, MAFs induce higher levels of proliferation, migration, invasion and drug resistance in tumor cells and promote their EMT and stemness phenotype, which is mediated by MAF-derived IGF2." (PMID 34112258, 2021). "Here, we found that reducing IGF2 expression levels or blocking IGF1R, using AEW541, combined with either isiPI3K, BYL719 or GDC0032, enhanced tumor growth arrest." (PMID 34067117, 2021). "Knocking-down IGF2 with siRNA, or blocking IGF1R with AEW541, resulted in superior anti-tumor activity of isiPI3K in vitro and ex vivo." (PMID 34067117, 2021). "The results indicated that the expression of tumor cell-derived VEGFA, IGFBP3, EFNA1, EFNB1, IGF2, PDGFA and stroma-derived Angpt2, Cdh5, Esam, Esm1, Icam2, and Tie1 was statistically correlated with that of Pecam1 and elevated in p-EMT TW2.6 tumors." (PMID 34869001, 2021). "Different families of RBPs are dysregulated in cancer such as the family of the insulin-like growth factor 2 mRNA binding proteins (IGF2BPs), which includes the paralogues IGF2BP1, IGF2BP2 and IGF2BP3 and plays an oncogenic role in different tumor models." (PMID 33673232, 2021). "Both of them showed a high expression in CRC tumor tissues and cells, IR-A seemed to be expressed higher than IGF1R which made IR-A to have a higher ability than IGF1R to interact with IGF2." (PMID 33173015, 2020). "Expectably, LIN28B-AS1 was depleted in LIN28B-AS1 KO tumor tissues, where IGB2BP1-dependent mRNAs, including Gli1, Myc, and IGF2, were decreased." (PMID 32917856, 2020). "The IGF2 mRNA-binding protein 1 (IGF2BP1) promotes the proliferation and in vivo growth of tumor cells derived from a variety of solid cancers." (PMID 32761127, 2020). "An increase in IGF2BP3 expression is associated with increased cell invasiveness and greater dynamics of the tumor process IGF2BP2, in turn, stabilizes IGF-2 mRNA, which increases its expression contributing to tumor development." (PMID 32850012, 2020). "Tumor cells with mesenchymal phenotype are resistant to the dual IGF-IR/InsR inhibitor linsitinib, due to the decreased expression of IGF2 and InsR, and phosphorylation of IGF-IR/InsR in these cells." (PMID 32493414, 2020). "The methylation alterations at H19/IGF2:IG-DMR and KCNQ10T1:TSS-DMR detected in the tumor samples were generally more intense than those affecting the other imprinted loci." (PMID 33217932, 2020).
tumor (continued). "Several gene alterations in predisposing loci have been well-identified, including mutations in Wilms' tumor gene 1 (WT1), catenin beta 1 (CTNNB1), insulin-like growth factor-2 (IGF2) and Wilms' tumor gene on the X chromosome (WTX)." (PMID 32318341, 2020). "Both HIF1 and IGF2 stimulate expression of VEGF and other growth factors, promoting tumor angiogenesis resulting in tumor progression and metastases." (PMID 32093152, 2020). "An intermediate to high staining for IGF2 (82%; median score 5; range 3–6) and IGF1R (65%; median score 4; range 2–6) was observed in most tumor tissues and for IGF2R (median score 5; range 4–6) in all ACCs." (PMID 30838516, 2019). "IRA has a higher affinity for IGF2 compared with the IGF1R and its expression in malignant tumor tissue has been suggested to be involved in cancer development." (PMID 30838516, 2019). "NICTH is commonly associated with excessive secretion of immature insulin-like growth factor (IGF)-2 precursor or IGF-1, by mesenchymal or epithelial tumor cells." (PMID 29166433, 2019). "Recent data on three other lncRNAs (miR-181a/135a/302c) showed that all of them function as tumor suppressors, repressing PLAG1/IGF2 signaling, and exert their effect on 5-fluorouracil (5-FU) chemoresistance through attenuation of PLAG1 expression." (PMID 31623387, 2019). "In this study, we examined the functional roles of IGF‐2 and MMP‐1 in mediating the tumor tropism of MSCs." (PMID 29321953, 2018). "When taking into account the different tumour subtypes, we detected 24 SNPs (in eight genes: ZDBF2, PEG10, MEST, H19, IGF2, MEG3, ZNF331 and HM13) exhibiting DI in at least one subtype compared to the normal tissue samples." (PMID 30297886, 2018). "To better elucidate the role of MMP‐1/IGF2/IGFBP2 in MSC tumor tropism, we analyzed the expression of IGFBP2 in MSCs with different tumor‐tropic properties by western blot analysis." (PMID 29321953, 2018). "Among the IGF2BPs, IGF2BP3 has been particularly described to favor IGF2 translation, thereby activating IGF signaling and promoting cell growth, proliferation, and resistance to ionic irradiation in different tumor types." (PMID 29731738, 2018). "In the present study, we further demonstrated that MMP‐1 secreted by the highly tumor‐tropic MSCs cleaved the IGF‐2/IGFBP2 complex that resulted in the release of free IGF‐2, which facilitated MSC migration toward tumor cells via the IGF‐2 signaling axis." (PMID 29321953, 2018). "It has been reported that the dysregulation of IGF2 and TIMP1 results in tumor invasion and metastasis." (PMID 30344796, 2018). "Conversely, IGF-1R expression decreases with cancer de-differentiation, suggesting that the IGF-2/IR-A loop exerts a more important role than the IGF-1/IGF-1R loop in thyroid cells de-differentiation, stemness, tumor progression, and metastasis." (PMID 30513575, 2018). "A candidate‐based screen of tumor lysates and differential protein arrays of cultured HSC identified several established hepatotropic cytokines, including IGF2, RBP4, DKK1, and CCL5 as being negatively regulated by endosialin." (PMID 28373218, 2017). "IMP2 stabilization of HMGA1 mRNA plus IMP2 stimulated IGF2 production synergistically drive cancer cell proliferation and account for IMP2’s tumor promoting action." (PMID 28753127, 2017). "Genes such as INHBA, IGF2, LGALS1, RHOJ, and THBS2 were upregulated in the tumor buds but downregulated in the microenvironment." (PMID 28687755, 2017). "The author states that the increased expression of IGF2 and IMP3 can promote tumor angiogenetic processes." (PMID 28439237, 2017).
tumor (continued). "Our findings, as presented here, indicate a benefit in TNBC outcomes by inhibiting IGF2 activity using targeted therapies against IGF1R/IR and AR to prevent tumor growth and potentially metastasis." (PMID 29099049, 2017). "To investigate the role of Id1-induced IGF2 on VEGF-mediated tumour angiogenesis, we first compared the microvessel density in subcutaneous tumour xenografts established from KYSE150-Id1-shCON, KYSE150-Id1-shIGF2 and KYSE150-CON-shCON ESCC cells." (PMID 28186102, 2017). "We used lentiviral vectors to transfect miR483 precursor (pre-miR483) and miR483-5p into two tumor cell lines (ASPC and HCT116) that maintain normal IGF2 imprinting." (PMID 27486969, 2017). "In IGF2 LOI tumor cell lines that express low levels of SUZ12, ectopic expression of SUZ12 restores normal IGF2 imprinting." (PMID 27486969, 2017). "While there is no consensus on a gene panel to determine the CIMP status of a tumour, one of the most commonly used is the Weisenberger panel of genes comprising of CACNA1G, NEUROG1, RUNX3, SOCS1 and IGF2." (PMID 28351398, 2017). "Taken together, these data showed that Id1-induced IGF2 from primary tumours can affect the tumour micro- and macroenvironment by systemically activating and mobilizing VEGFR1+ BMDCs to facilitate tumour growth and metastasis." (PMID 28186102, 2017). "Our meta-analysis was unable to find any statistical significance between HCC tumor tissues and adjacent tissues for the methylation of the remaining four genes, including MGMT, DAPK1, IGF2 and RB1." (PMID 27835605, 2016). "Downregulation of miR-615-5p limits its inhibitory effect on IGF-2 and other targets, such as proto-oncogene JUNB, which results in increased tumor growth, invasion and migration capabilities in PDAC cells." (PMID 27240340, 2016). "Human MYOD1 gene is located at 11p15, a chromosomal region containing the IGF2 and H19 imprinted genes, whose expression has been found to be altered (over-expression of IGF2 and downregulation of H19) in a subset of ERMS tumours." (PMID 27764816, 2016). "Microarray-based mRNA expression levels confirmed higher expression of IRS1, IGF2, IGF1R and AR in “NFκB off” compared to the “NFκB on” tumours in all five datasets." (PMID 26943587, 2016). "The meta-analysis of p14, p15, p73, APC, SOCS1, MGMT, SFRP1, PRDM2, DAPK1, RARβ, IGF2 and hMLH1 genes methylation was performed between HCC tumor tissues vs adjacent tissues and HCC tumor tissues vs normal tissues." (PMID 27835605, 2016). "The high expression of IGF2 was maintained in the metastasis; moreover the expression of its receptor IGF1R was slightly upregulated in the primary tumor and the metastasis." (PMID 27825128, 2016). "Recently, it was demonstrated that abnormal miR-615-5p downregulation due to promoter hypermethylation limits its inhibition of IGF2 and other targets in PDAC cells, resulting in increased tumor growth, invasion and migration capabilities." (PMID 25856297, 2015). "The frequencies of hypermethylation for IGF2 and NEUROG1 were significantly increased in all tumor types when compared to normal colon." (PMID 26203307, 2015). "Given that the downstream intracellular targets of CXCL8 include STAT3, increased CXCL8 in the tumour stroma promotes a positive intercellular feedback loop between CXCL8 and IGF-2 production." (PMID 26465273, 2015). "Although there are two receptors for IGFs, IGF-1R and IGF-2R, IGF-2R does not transduce a signal and acts to reduce the bioavailability of IGF-2 by sequestering it away from IGF-1R and thus acts as a tumor suppressor." (PMID 24885964, 2014). "In the present case, the mRNA expression of both IGF1 and IGF2 has increased (FDR = 4.65E-35 and FDR = 3.46E-15, respectively); however, the expression of IGF1R remained the same in the tumour tissue compared to that in the control tissue." (PMID 25496518, 2014). "IGF2 is highly expressed in human HCC, where it seems to have a stimulatory effect on tumour cell proliferation." (PMID 25225571, 2014).